CAT (catalase)
Diseases named in the same sentence as CAT in open-access papers (continued):
Sharing a sentence is not in itself a finding about the gene and the disease.
metabolic syndrome (continued). "Under certain conditions, including dyslipidemia, cells will overproduce ROS, and several response mechanisms will be activated, including enzymatic antioxidants such as SOD and CAT." (PMID 38283628, 2024). "According to these data, a variety of mechanisms, such as an increase in the levels of free radical scavenging including glutathione peroxidase (GPx), CAT, SOD, as well as GSH are involved in the reduced activity of dyslipidemia and MDA content." (PMID 37396948, 2023). "When compared to the metabolic syndrome rats that received the vehicle, AO at doses of 1, 10, and 100 mg/kg BW increased SOD, CAT, and GSH-Px in the cerebral cortex (p-value < 0.001 all; p-value < 0.01 all; p-value < 0.01, 0.001, and 0.001)." (PMID 36358575, 2022). "In an ‘ex vivo’ setting, nitrate intake avoids the enhanced expression of CAT and TNFα induced by PMA in PBMCs from metabolic syndrome patients but, on the other hand, it activates the expression of GPx in response to PMA stimulation." (PMID 34198661, 2021). "Melatonin intake at a dosage of 5 mg/day for 8 weeks among people with metabolic syndrome reduced MDA levels and enhanced catalase activity." (PMID 31139144, 2019). "In the present study, ethanol extract from RTL improved dyslipidemia, increased SOD and catalase activity in the aortic tissues of HFD and STZ‐induced T2DM rats." (PMID 31763023, 2019). "Here, we examined the effect of MEHI on dyslipidemia and increased SOD, CAT and GPX activity of the aorta, heart, and liver in rats." (PMID 27761421, 2016). "These markers are crucial for assessing the redox balance in metabolic syndrome and include malondialdehyde (MDA), superoxide dismutase (SOD), catalase (CAT), glutathione (GSH), total oxidative status (TOS), total antioxidant capacity (TAC), and other antioxidant enzymes." (PMID 40868165, 2025). "On the other hand, following a HFD consumption for 30 days body weight, energy intake, plasma glucose, dyslipidemia, and oxidized-LDL in the liver tissue were increased while no significant change was reported in GSH content and activity of SOD and catalase enzymes." (PMID 38975085, 2024). "In another study, TNF-α and IL-6 concentrations and myeloperoxidase activity were higher (whereas catalase and superoxide dismutase activities were lower) in consumers with a high intake of ultra-processed food (UPF) with metabolic syndrome than in those with a low intake of UPF." (PMID 38542788, 2024). "Blood markers of oxidative stress including superoxide dismutase (SOD), catalase (CAT), and nitric oxide (NO) were elevated in patients with AS combined with metabolic syndrome (MetS), but glutathione peroxidase (GPX) and TOS levels were not significantly changed." (PMID 37032771, 2023). "However, this acute exercise performed by metabolic syndrome patients reduces the gene expression of CoxIV and Tfam and maintains the basal expression of MitoND5, UCP3, HO1, MnSOD, GPx, CAT, Mfn1, Mfn2, Nrf2 and PGC1α." (PMID 34198661, 2021). "Although the phytochemical extract of willow bark, which contains salicylates, as well as aspirin, increases CAT activity in animal models of dyslipidemia, research conducted on our KOA model did not yield statistically significant results regarding the effect of SaIONPs on CAT." (PMID 38785813, 2024). "Additionally, JPP treatment recovered T2DM dyslipidemia in a dose-dependent manner and restored nonenzymatic antioxidant defences (NPSH and GSH/GSSG ratio), without changes in the enzymatic antioxidant defences (SOD, CAT, TrxR-1, GPx, and GST activities)." (PMID 30186630, 2018).
lung carcinoma (55 papers, 2009 to 2026). "PURPOSE: To explore the relationship between ATM, ATR and CAT polymorphisms and prognosis of lung cancer patients received platinum-based chemotherapy." (PMID 36969849, 2023). "Herein, we investigated the association of potentially functional SNPs in ATM, ATR and CAT with platinum-based chemotherapy outcome of lung cancer patients." (PMID 36969849, 2023). "Association of comorbidities with CAT genotypes in lung cancer patients." (PMID 36969849, 2023). "The proposed associations in the antioxidant system in lung cancer remain speculative, and require further research, including assessment of GPx and CAT activity." (PMID 34832849, 2021). "In a benzo(a)pyrene-induced lung cancer model, the upregulation of CAT through hyperoxia combined with carboplatin significantly enhanced apoptosis, indicating a synergistic interaction between oxidative stress and chemotherapy." (PMID 40722961, 2025). "Treatment with capsaicin, an ingredient of red pepper, restores CAT activity in a benzo(a)pyrene-induced lung cancer mouse model." (PMID 40722961, 2025). "For example, catalase-loaded nanoparticles have been shown to generate oxygen in situ, boosting the immune response in murine models of melanoma and lung cancer." (PMID 41048631, 2025). "Consistently, it has been documented that CAT is lowly expressed in early-stage lung cancer tissues." (PMID 40496615, 2025). "In our previous study, we showed that CAT also significantly reflected the changes in HRQL of lung cancer." (PMID 38360680, 2024). "Silymarin treatment (58 μM/ml) significantly reduced the activities of both SOD and CAT in A549 lung cancer cells." (PMID 39431222, 2024). "The top candidate exosomal proteins associated with lung cancer, based on the number of publications supporting the association, included SPP1, CD44, ALB, SPARC, CAT, GAPDH, and CADM1." (PMID 39766023, 2024). "The bioinformatics-based association analysis identified candidate exosomal proteins associated with lung cancer, including SPP1, CD44, ALB, SPARC, CAT, GAPDH, and CADM1." (PMID 39766023, 2024). "RESULTS:CAT rs769217 was significantly related to PFS of patients with lung cancer who received platinum-chemotherapy." (PMID 36969849, 2023). "In conclusion, our study showed that CAT rs769217 is significantly related to PSF of platinum-based chemotherapy in lung cancer patients." (PMID 36969849, 2023). "CCK-8, Edu and transwell assays were conducted to analyze the role of CAT on cell proliferation migration and invasion in lung cancer." (PMID 36467027, 2022). "The protein expression levels of ALDOA, ENTPD2, LDHA, TYMS and CAT were investigated in 5 lung cancer cell lines (A549, H460, H1299, H1975, PC9), normal airway epithelial cells (16HBE) as control." (PMID 33858449, 2021). "Catalase expression is also inhibited by miR-551b in human lung cancer cells and the miR-551b/CAT pathway can be involved in acquired apoptosis resistance and chemoresistance through interaction with MUC1." (PMID 34199590, 2021). "Biochemical parameters (catalase, imidazole compounds ICs, sialic acids, lactate dehydrogenase (LDH)) that can be used to monitor patients at risk (COPD I) for timely diagnosis of lung cancer are determined." (PMID 33333922, 2020). "Another study showed reduced catalase activity in lung cancer due to its protein and mitochondrial RNA (mRNA) reduction in tumor cells." (PMID 29565268, 2018). "In lung cancer cells, miR-551b inhibits the expression of catalase and enhances the accumulation of reactive oxygen species and the expression of mucin-1, contributing to the acquired resistance to apoptosis and chemotherapy." (PMID 27743201, 2016). "In this study antioxidant supplements reduced the exonic expression of ROS enzymes including catalase, GPXs and SODs in the murine lung cancer dataset." (PMID 26805894, 2016). "For example, catalase expression and activity is extinguished in lung cancer, whereas the cytoplasmic peroxidase PRX1 is highly over-expressed." (PMID 26011724, 2015).
lung carcinoma (continued). "Studies are limited regarding the role of catalase in pulmonary fibrosis in humans, although catalase was found to be decreased in airway epithelium exposed to 100% O2, in lung cancer, and in asthma." (PMID 21190578, 2010). "cAT levels associated significantly with PADI4 levels in patients with hepatocellular carcinomas, lung cancer, ovarian cancer, endometrial carcinomas and thyroid adenomas (p < 0.01)." (PMID 19183436, 2009). "Thus, CAT downregulation contributes to an oxidative environment that is favorable for lung cancer initiation and progression." (PMID 40722961, 2025). "CAT activity is reduced or dysregulated in lung cancer cells and tissues." (PMID 40722961, 2025). "In the chemotherapy resistance of lung cancer, miR-551b promotes the sensitivity of cells to apoptotic toxicity induced by chemotherapeutic agents by reducing the expression of cell catalase, inhibiting the accumulation of reactive oxygen species and the expression of MUC1 protein." (PMID 38572416, 2024). "CAT rs769217 may be a biomarker for predicting the prognosis of lung cancer patients with platinum-based chemotherapy." (PMID 36969849, 2023). "Similarly, cryptotanshinone (CTS), a bioactive component of Salvia miltiorrhiza, was shown to sensitize gefitinib‐resistant EGFR‐mutant lung cancer cells by targeting catalase (CAT), heme oxygenase 1 (HMOX1) and stearoyl‐CoA desaturase (SCD)." (PMID 37697969, 2023). "But the impact of CAT polymorphism on the prognosis of patients with lung cancer receiving platinum chemotherapy has not been reported." (PMID 36969849, 2023). "Our results suggest that CAT rs769217 may affect the PFS of lung cancer patients receiving platinum-based chemotherapy." (PMID 36969849, 2023). "In order to test the marker genes of B2-protein-induced stress signals, such as Nrf2, catalase, MnSOD, and Cu/ZnSOD, at the mRNA level, we examined its effect on an A549 lung cancer cell-induced solid tumor grafted on NOD/SCID mice using the real-time q-PCR approach." (PMID 36672696, 2023). "Interestingly, CAT was found downregulated in human lung cancer, suggesting that lung cancer cells are sensitive to oxidative stress." (PMID 35370706, 2022). "The hub genes CAT (HR = 0.6, P-value = 2.6e − 15, log2FC = − 1.3802) and APP (HR = 0.81, P-value = 0.0012, log2FC = − 1.1716) were significantly associated with an unfavorable overall survival in lung cancer patients." (PMID 36302939, 2022). "Similarly to HCG, gelatin nanoparticles have been reported to decrease the activities of SOD, GSH-PX and CAT during apoptosis of NCI-H460 lung cancer cells." (PMID 34821368, 2021). "CAT was significantly decreased in 5 lung cancer cell line, comparing with in 16HBE." (PMID 33858449, 2021). "The revealed biochemical parameters (catalase, imidazole compounds, sialic acids, LDH) can be used to monitor patients from risk groups, for example, groups of patients with initial stages of COPD, in particular for the timely diagnosis of lung cancer." (PMID 33333922, 2020). "One recent study has demonstrated that the activities of different SOD isotypes and catalase are low in lung cancer cells than adjacent normal cells; however, the activities of GPX, glutathione reductase, and glutathione S-transferase are higher in lung cancer cells." (PMID 32937815, 2020). "Indeed, both vitamin E treatment and cytosolic catalase overexpression were able to rescue lung cancer cells from apoptosis." (PMID 33317057, 2020). "Reduction of CAT and GPx protein expressions was demonstrated in neoplastic tissues of patients with esophageal, colorectal, and lung cancers, although both downregulation and overexpression of MnSOD protein in lung and esophageal cancers, respectively, were reported." (PMID 27057281, 2016). "Interestingly, we also found that in RIP1 knockdown lung cancer cells, miR-146a was increased, leading to catalase suppression." (PMID 24675421, 2014).
lung carcinoma (continued). "Studies have shown that CAT rs769218 is related to the prognosis of gastric cancer patients receiving platin and fluorouracil-based adjuvant therapy, but the correlation between the prognosis of lung cancer patients and CAT polymorphism has not been reported." (PMID 36969849, 2023). "Moreover, overexpression of CAT could decrease the proliferation, invasion and migration of lung cancer cells." (PMID 36467027, 2022). "Thus, it was examined whether Tempol influenced the expression and activity of SOD, catalase, Trx1, and TrxR1 in lung cancer and normal cells at 48 h." (PMID 34290305, 2021). "There was a strong correlation between the survival time of individuals with lung cancer and 7 genes (CLEC3B, AOC3, HBB, CAT, SEPP1, FGA, and ORM1, P<0.05)." (PMID 40496615, 2025). "The C-type lectin domain family 3 member B (CLEC3B), membrane primary amine oxidase (AOC3), hemoglobin subunit beta (HBB), catalase (CAT), and selenoprotein P (SEPP1) were screened as candidate protein markers for early-stage lung cancer." (PMID 40496615, 2025). "The candidate protein markers (AOC3, CAT, CLEC3B, SEPP1, HBB) and traditional tumor markers (CEA, CYFRA21-1, NSE) were combined to construct screening models for lung cancer by machine learning techniques." (PMID 40496615, 2025). "The candidate protein markers were investigated based on the TCGA database, supplemented by Kaplan-Meier plotter and Oncomine analysis, and then AOC3, CLEC3B, CAT, SEPP1, and HBB were selected as potential candidates for early-stage lung cancer." (PMID 40496615, 2025). "When compared to controls, it was found that the lung cancer group of rats had changed MDA, GSH, GR, CAT, and SOD activities; however, these activities simply reversed and returned to the closest point to the normal control value of rats." (PMID 37765117, 2023). "The lung cancer group of rats had changed MDA, GSH, GR, CAT, and SOD activities; however, these activities simply reversed and returned to the closest point of the normal control group of rats by administering BQ-SLN3." (PMID 37765117, 2023). "In a rat model of lung cancer, administration of CUR and resveratrol decreased Cyt c activity and oxidative enzymes, increased lipid peroxidation, SOD and CAT activities and reduced LPO." (PMID 37697969, 2023). "Therefore, CTS may sensitize lung cancer cells to gefitinib by inhibiting CAT." (PMID 35370706, 2022). "On the other hand, the CAT, SOD, and GPX activity enzymes dramatically decreased in 20, 40, and 60 μM TQ compared to control cells, according to earlier research on the A549 lung cancer cell line." (PMID 36432484, 2022). "The mRNA expression levels of CAT, ENTPD2 and LDHA were also investigated in 6 lung cancer cell lines (A549, H460, H1299, H1975, PC9, Lewis), 16HBE as control." (PMID 33858449, 2021). "Herein, a multi-functional nanoplatform Nb@IC was designed by using of anti-EGFR Nb combined with photosensitizer and catalase (Cat) to improve tumor hypoxia, enhancing the therapeutic efficacy of PDT of IR1048MZ in lung cancer." (PMID 33292202, 2020). "The increase of oxidative stress in lung cancer cells treated with BA6 was accompanied by a decrease in the expression of antioxidant enzymes Cu/Zn SOD, MnSOD, and catalase." (PMID 31205586, 2019). "Luteonin induced human lung carcinoma cell apoptosis was accompanied by activation of antioxidant enzymes such assuperoxide dismutase (SOD) and catalase (CAT)." (PMID 22058652, 2011). "The expressions of candidate protein markers were dynamically observed at the various phases of lung carcinogenesis, which revealed that AOC3, CAT, CLEC3B, SEPP1, and HBB may be the key molecular markers of early lung cancer lesions." (PMID 40496615, 2025).
lung carcinoma (continued). "Finally, the screening models for lung cancer were constructed by combining candidate protein markers (AOC3, CAT, CLEC3B, SEPP1, HBB) with tumor markers (CEA, CYFRA21-1, NSE) using machine learning." (PMID 40496615, 2025). "In this study, we determined that metformin reduced the survival of lung cancer cells, induced oxidative stress through increasing intracellular ROS and MDA levels while reducing intracellular GSH, T-SOD and CAT contents, and increased the accumulation of cellular ferrous ions." (PMID 37749553, 2023). "Finally, administration of TQ (50 mg/kg) decreased NFk‐B expression, ROS, MDA and NO levels and increased apoptosis and CAT and SOD activity in B(a)P‐induced lung cancer in rats." (PMID 37697969, 2023). "For CAT, with negative staining both in lung cancer tumor cells and normal pneumocytes, no significant expressional difference was shown." (PMID 32265992, 2020). "In the present investigation, levels of the antioxidant enzyme SOD1, but not those of SOD2 or catalase, were significantly greater in the tumors of the lung cancer-bearing mice treated with the monoclonal antibodies." (PMID 31487876, 2019). "CONCLUSION:CAT rs769217 is significantly related to PSF of platinum-based chemotherapy in lung cancer patients and may be a biomarker for predicting the prognosis of lung cancer patients with platinum-based chemotherapy." (PMID 36969849, 2023). "For example, antioxidant enzymes including superoxide dismutase (SOD), catalase (CAT), and glutathione peroxidase (GPX) are all reduced in NSCLC in comparison with corresponding controls, and glutathione (GSH) and its related enzymes that detoxify ROS, are increased in lung cancer." (PMID 36052170, 2022). "However, it is possible that the downregulated basal activities of caspases by their inhibitors improve the basal intact forms of antioxidant enzymes, such as SODs, catalase, and GSH peroxidase, to strongly scavenge basal ROS levels, including O2∙−, in lung cancer cells." (PMID 35889456, 2022). "Therefore, the expression levels of catalase in lung cancer and normal cells did not correlate with its enzymatic activity." (PMID 34290305, 2021). "In this study, CAT activity in NSCLC patients was significantly high (p = 0.00001) in the adjacent noncancerous tissues, irrespective of the different histological types of lung cancer." (PMID 31781331, 2019).